TECRP1 (trans-2,3-enoyl-CoA reductase pseudogene 1)
Gene: Transcribed processed pseudogene on chromosome 4 (86,949,669 to 86,950,113, reverse strand). Ensembl gene ENSG00000235043.
Diseases named in the same sentence as TECRP1 in open-access papers:
TECRP1 is named in the same sentence as 1 disease in open-access papers, as found by Europe PMC text mining. Sharing a sentence is not in itself a finding about the gene and the disease.
TECRP1 shares sentences with these, for which no sentence is quoted: breast carcinoma (1 paper).